CHMP7 (charged multivesicular body protein 7)
Diseases named in the same sentence as CHMP7 in open-access papers:
CHMP7 is named in the same sentence as 23 diseases in open-access papers, as found by Europe PMC text mining. Sharing a sentence is not in itself a finding about the gene and the disease. The quoted sentences say what the papers report.
amyotrophic lateral sclerosis (3 papers, 2019 to 2023). Amyotrophic lateral sclerosis (ALS) is a neurodegenerative disease characterized by progressive muscular paralysis reflecting degeneration of motor neurons in the primary motor cortex, corticospinal tracts, brainstem and spinal cord. "Interestingly, aberrant nuclear accumulation of CHMP7 is associated with diseased neurons from patients with amyotrophic lateral sclerosis and reduces NPC levels." (PMID 37795681, 2023). "CHMP7 is also associated with the pathogenesis of amyotrophic lateral sclerosis." (PMID 36246601, 2022).
Sepsis (3 papers, 2022 to 2023). Sepsis is defined as life-threatening organ dysfunction caused by a dysregulated host response to infection. "Our results revealed that the expression of CHMP7 was significantly lower in sepsis patients and a higher expression of CHMP7 was associated with a better prognosis." (PMID 36618365, 2022). "The results of the ROC analysis illustrated the satisfactory diagnostic ability of CHMP7, NLRC4, and PLCG1 for sepsis." (PMID 37939116, 2023). "The study identified seven important PRGs including CHMP7, NLRC4, PLCG1, IRF1, CASP4, NLRP1, GSDMD associated with sepsis." (PMID 37939116, 2023). "According to the ROC curves, four out of six genes (GZMB, CHMP7, NLRP1, and AIM2) had good diagnostic value in the diagnosis of sepsis, with AUC > 0.9 in both the GSE65682 and GSE95233 datasets." (PMID 36618365, 2022). "Four out of six genes (GZMB, CHMP7, NLRP1, and AIM2) also have potential diagnostic value in sepsis diagnosis." (PMID 36618365, 2022). "In both datasets, the expression level of AIM2, ELANE, and MYD88 were significantly higher in sepsis patients compared to healthy individuals, while the expression level of CHMP7, GZMB, and NLRP1 were significantly lower." (PMID 36618365, 2022). "Due to the limited number of studies, the role of CHMP7 in sepsis remained unclear and our study may provide some insights for future study." (PMID 36618365, 2022). "The qRT-PCR results showed that the expression of CHMP7 was downregulated, while NLRC4 and PLCG1 expression was upregulated in H9C2 cells stimulated with LPS to mimic in vitro sepsis model." (PMID 37939116, 2023). "In addition, the expression of CHMP7, NLRC4, and PLCG1 in an in vitro sepsis model was further validated." (PMID 37939116, 2023). "Then, we developed a prognostic risk score with six pyroptosis-related genes, including GZMB, CHMP7, NLRP1, MYD88, ELANE, and AIM2, and found that it could predict the prognosis of sepsis patients." (PMID 36618365, 2022).
colorectal cancer (2 papers, 2022 to 2023). A primary or metastatic malignant neoplasm that affects the colon or rectum. "In this study, the differential expression of CHMP7 in multiple tumor tissues was analyzed with information from public databases and clinically collected colorectal cancer tissue samples." (PMID 37711849, 2023).
gastric cancer (2 papers, 2012 to 2022). A primary or metastatic malignant neoplasm involving the stomach. "CHMP7 was identified as a prognostic biomarker in gastric cancer." (PMID 35432539, 2022).
diabetes (1 paper, 2023). "The results indicated that CHMP7 expression level was not significantly correlated with patients’ age, weight, gender, concomitant disease status (hypertension and diabetes), and T-stage, and the group with low CHMP7 expression had advanced N-stage and TNM-stage." (PMID 37711849, 2023).
esophageal cancer (1 paper, 2025). A primary or metastatic malignant neoplasm involving the esophagus. "Further investigating the role of CHMP7 in immune invasion of esophageal cancer, we ultimately found a positive correlation with Treg cells (0.393; p=4.97e-08) and CD8+ T cells (0.147; p=4.97e-2), when CHMP7 was analyzed for correlation with different immune cells." (PMID 40083549, 2025). "It indicating that CHMP7 may interact with immune cells to affect the occurrence and development of esophageal cancer." (PMID 40083549, 2025). "In addition, we upregulated the expression of CHMP7 in esophageal cancer cells by transfecting overexpressing plasmids, and subsequently observed a significant increase in cell proliferation." (PMID 40083549, 2025).
Immunodeficiency (1 paper, 2025). Failure of the immune system to protect the body adequately from infection, due to the absence or insufficiency of some component process or substance. "The CHMP7 gene has been associated with immunodeficiency, translation regulation, membrane deformation, cell division, metabolism, and development; notably, its low expression may impair these biological processes." (PMID 41144480, 2025).
lung adenocarcinoma (1 paper, 2019). A carcinoma that arises from the lung and is characterized by the presence of malignant glandular epithelial cells. "Higher CHMP7 and cGAS44 RNA expression correlate with higher frequency of patient survival in lung adenocarcinoma, a tumor with high levels of chromosomal instability." (PMID 30988276, 2019).
motor neuron disease (1 paper, 2022). "Further, transcriptomic profiling of motor neurons in mice models of spinal and bulbar muscular atrophy (SBMA—another degenerative motor neuron disease) identified that the CHMP7 transcript was downregulated, potentially implicating CHMP7 function in the disease pathogenesis." (PMID 35163252, 2022).
primary immunodeficiency (1 paper, 2022). "CHMP7 was closely related to complement and coagulation cascades, oxidative phosphorylation, primary immunodeficiency, ribosome, and splicesome." (PMID 36685920, 2022). "Notably, high CHMP7 expression activated glycosphingolipid biosynthesis lacto and neolacto series, complement and coagulation cascades, and folate biosynthesis, whereas the low expression of CHMP7 activated primary immunodeficiency, RNA polymerase, and ribosome." (PMID 36685920, 2022).
squamous cell carcinoma of (1 paper, 2023). "Charged multivesicular body protein 7 (CHMP7) has been shown to be a risk gene for squamous cell carcinoma of the head and neck." (PMID 37302999, 2023).
synucleinopathy (1 paper, 2025). A neurodegenerative disease that is characterized by the abnormal accumulation of aggregates of alpha-synuclein protein in neurons, nerve fibers or glial cells. "Western blots were performed on synucleinopathy and control Neuro 2a cells reveals differential expression of LEMD2 and the ESCRT-III component CHMP7." (PMID 40654851, 2025).
viral infection (1 paper, 2022). "The protein levels of these ESCRT subunits (HRS, VPS28, VPS25, CHMP2B, CHMP4B, CHMP7, VPS4A and ALIX) in the VRC were significantly increased by the viral infection in a dose-dependent manner." (PMID 35120190, 2022).
tumor (13 papers, 2019 to 2025). "We designated CHMP7 in the 6-gene prognostic risk model as a potential target to improve tumor cell prognosis." (PMID 40083549, 2025). "All analyses suggest that CHMP7 is altered in various tumor tissues and associated with genomic instability." (PMID 37711849, 2023). "The results suggest that CHMP7 is associated with many immune cells, with the possible involvement of killing tumor cells by targeting CTLs." (PMID 37711849, 2023). "CHMP7 plays a significant role in the endosomal sorting pathway, and the deficient expression of CHMP7 in the majority of tumor tissues has been reported." (PMID 35783272, 2022). "Si-CHMP7 transfection led to a decrease in tumor cell migration, invasion, and proliferation, accompanied by an accelerated apoptotic process." (PMID 40083549, 2025). "The differential expression of CHMP7 in tumor tissues and corresponding normal tissues were analyzed with TCGA, TARGET, and GTEx databases." (PMID 37711849, 2023). "CHMP7 can potentially serve as a new biomarker for predicting the efficacy of tumor chemotherapy and immunotherapy." (PMID 37711849, 2023). "The differential expression of CHMP7 in tumor and normal tissues was first compared, and the predictive value of CHMP7 for patient OS was assessed further." (PMID 37711849, 2023). "The tumor data from the TCGA database were exploited to analyze the correlations between CHMP7 and multiple pathways, and the results were represented as scatter plots." (PMID 37711849, 2023). "The low CHMP7 expression group was associated with poor prognosis in BRCA, COAD, HNSC, and KIRC, and the level of CHMP7 expression decreased with a more advanced tumor stage." (PMID 37711849, 2023). "CHMP7 shows a predictive value for the prognosis of patients with tumors and is highly involved in tumor immunity." (PMID 37711849, 2023). "To investigate the possible role of CHMP7 in tumor therapy, we investigated the predictive value of CHMP7 compared to classical biomarkers for immunotherapeutic response through the TIDE website." (PMID 37711849, 2023). "In this study, the differential expression of CHMP7 in tumor tissues and its prognostic impact were systematically analyzed with information from public databases such as TCGA, CCLE, and GTEX." (PMID 37711849, 2023). "The role of CHMP7 in tumor immunity is a central focus of our study and excels as a biomarker for predicting the efficacy of tumor immunotherapy and chemotherapy." (PMID 37711849, 2023). "A pan-cancer study shows that CHMP7 is low expressed in most tumor tissues, and patients with low expression have a poor prognosis." (PMID 37663658, 2023). "The TISMO website was utilized to compare the changes in CHMP7 expression levels in tumor cell lines in both pre- and post-cytokine treatment." (PMID 37711849, 2023). "In this article, we utilized public databases such as TCGA, GTEx, TARGET, and single-cell sequencing data to provide a comprehensive and intensive analysis of the role of CHMP7 in tumor development and therapy." (PMID 37711849, 2023). "DNAss is a cancer stemness score based on the methylation profile calculated for each tumor and further analyzed for CHMP7 DNA methylation in the TCGA database." (PMID 37711849, 2023). "The dysregulation of ESCRT function is highly related to tumor development, and CHMP7, an important regulatory subunit of ESCRT-III, has attracted our attention." (PMID 37711849, 2023). "In this study, CHMP7 has been comprehensively described with the help of public databases of tumor tissues." (PMID 37711849, 2023). "All these results indicate that AS events of CHMP7 are critical in tumor research." (PMID 37711849, 2023). "The negative correlation of CHMP7 with tumor-associated macrophages has been observed in BLCA, COAD, HNSC, LAML, PAAD, and PRAD, while the opposite has been observed in CHOL, GBM, KIRP, LIHC, and THYM." (PMID 37711849, 2023).
tumor (continued). "The correlation between CHMP7 and cancer stemness was analyzed based on six tumor stemness indices calculated by mRNA expression and methylation signature, which were significantly positively correlated in HNSC and negatively correlated in LUAD, COAD, COADREAD, BRCA, THYM, PCPG, and BLCA." (PMID 37711849, 2023). "The results suggest that downregulated CHMP7 levels may lead to the occurrence of tumor drug resistance." (PMID 37711849, 2023). "A strong correlation between CHMP7 and TME immune cell infiltration has been observed, participating in the formation of suppressive TME and promoting tumor progression." (PMID 37711849, 2023). "A strong correlation between CHMP7 and TME immune cell infiltration has been observed, which is involved in the formation of suppressive TME and promotes tumor progression." (PMID 37711849, 2023). "In this study, CHMP7 was significantly and positively correlated with MMR and HRR-related gene signatures in various tumor tissues." (PMID 37711849, 2023). "The UALCAN website analyzed the differences in CHMP7 protein levels, revealing that CHMP7 protein was downregulated in BRCA, COAD, and UCEC tumor tissues and upregulated in LUAD tumor tissues." (PMID 37711849, 2023). "CHMP7 and angiogenesis, apoptosis, inflammatory response, EMT markers, tumor proliferation signature, and tumor inflammation signature all demonstrated a significant positive correlation." (PMID 37711849, 2023). "As the immune cell that primarily kills tumor cells in TME, lower CHMP7 expression significantly inhibits the function of CTL, further leading to tumor progression and poor patient prognosis." (PMID 37711849, 2023). "To investigate the relationship between CHMP7 and immune infiltration in the tumor TME, we calculated the stromal and immune scores of tumor samples based on CHMP7 expression data using the ESTIMATE package of R software." (PMID 37711849, 2023). "In the 27 PRGs, apart from CASP4, CHMP6, CHMP7, GSDMD, and TP63, the other 22 PRGs were expressed differentially at a significant level between primary tumor and paracancerous samples." (PMID 35938142, 2022). "Some of these genes (CHMP7, XPO7, KIAA1967) are reported to be tumor suppressor genes." (PMID 38896472, 2024). "CHMP7 is highly expressed in ES tumor tissues when compared to normal tissues, and the high-expressing group has a poor prognosis." (PMID 37663658, 2023). "Radar plots present the correlation between CHMP7 and TMB, and MSI in different tumor tissues." (PMID 37711849, 2023). "A significant negative correlation was observed between CHMP7 and DNA methylation probe cg00140501 in several tumor tissues of TCGA, including ACC, BRCA, BLCA, COAD, LIHC, and LUAD." (PMID 37711849, 2023). "Interaction network results revealed that BAK1, NLRP1, CHMP7, and RIPK1 genes could interact with immune factors, including TNF-α, suggesting their influence on the immune microenvironment of the HNSCC tumor." (PMID 36246601, 2022).
cancer (11 papers, 2019 to 2025). A tumor composed of atypical neoplastic, often pleomorphic cells that invade other tissues. "Together these data argue that LRRC59, LEMD2, and CHMP7 together control repair of MN and accumulation of DNA damage in ruptured MN, a major pathophysiological event associated with cancer progression." (PMID 41387506, 2025). "Initially, we explored the correlation between CNV and mRNA expression in 14 RMS model-associated genes in 33 kinds of tumors and revealed that CHMP7 expression was significantly modulated by CNV in almost all cancers, followed by SEPHS1 and AASDHPPT." (PMID 37124622, 2023). "The Cancer Dependency Map (DepMap) results showed that CHMP7 is associated with ES cell growth, and the Gene Set Cancer Analysis (GSCALite) results revealed that the JAK1 mutation frequency was the highest." (PMID 37663658, 2023). "Cancer cell death resistance is correlated with the activation of the CHMP7-associated ESCRT-III pathway." (PMID 36685920, 2022). "The influence of CHMP7 on chemotherapy and immunotherapy was evaluated to predict the effect of immunotherapy and sensitive drugs against CHMP7 in these cancers." (PMID 37711849, 2023). "A statistical relationship was found between CHMP7 expression levels and the clinical prognosis of cancer patients, and protein phosphorylation and immune cell infiltration processes were established." (PMID 36246601, 2022). "Based on the density of local network regions, we predicted CHMP7, NPR2, and TUBB6 as novel pathogenic genes whose splice variants impact the interaction network similarly as splice variants of cancer-associated genes." (PMID 32879328, 2020). "These include post-mitotic resealing of the NM and repair of NM ruptures produced during migration of cancer and immune cells through tight interstitial spaces, both of which require CHMP7 as an adaptor for ESCRT-III." (PMID 33139753, 2020). "Shear isoforms of CHMP7 in pan-cancer were also demonstrated." (PMID 37711849, 2023). "CHMP7 labeling of micronuclei was observed at a similar frequency across several cancer cell lines." (PMID 30988276, 2019). "Our VPS4KD data imply the existence of a similar mechanism; hence, the accumulation of CHMP7 and CHMP4B at micronuclei observed in unperturbed cancer cells implies the normal balance between ESCRT-III assembly and disassembly is impaired and/or is not regulated by VPS4 (VPS4-independent pathway)." (PMID 30988276, 2019). "Moreover, CHMP7 has been identified as gene that negatively regulates cell proliferation (STOP gene), in a study showing how recurrent deletions occurring in cancers drive tumorigenesis." (PMID 30988276, 2019). "In summary, the co-enrichment of ESCRT-III and RPA/cGAS at a subset of micronuclei and the absence of RPA/cGAS enrichment upon CHMP7 depletion, point to a non-canonical (VPS4-independent) function for ESCRT-III in maintaining a pool of cytosolic DNA in cancer cells." (PMID 30988276, 2019).
infection (2 papers, 2022 to 2025). The state of being infected such as from the introduction of a foreign agent such as serum, vaccine, antigenic substance or organism. "Finally, we infected these cells with MCPyV-GFP and found that PsV infection was enhanced by nearly 3-fold under CHMP7 KD conditions compared to the scrambled control." (PMID 40445976, 2025).
CHMP7 also shares sentences with these, for which no sentence is quoted: breast carcinoma (1 paper); COVID-19 (1); entropion (1); glioma (1); Hypertension (1); lung carcinoma (1); prostate carcinoma (1).